APOE (apolipoprotein E)
Diseases named in the same sentence as APOE in open-access papers (continued):
Sharing a sentence is not in itself a finding about the gene and the disease.
atherosclerosis (continued). "Long-term high dose nitrate significantly attenuated the progression of established atherosclerosis in the apoE−/− mice fed a HFD." (PMID 36853380, 2023). "In a model of atherosclerosis in apoE−/− mice, HTyr administration (10 mg/kg/day orally, for 16 weeks) significantly reduced the extent of aorta atherosclerotic lesions as well as serum CRP, TNF-α, IL-1β and IL-6 levels, while it increased IL-10." (PMID 37049611, 2023). "Although ApoE−/− was highly absorbed in the atherosclerotic aorta, the concentration of nanobodies was lower in atherosclerosis with a higher score." (PMID 37375810, 2023). "Continuous hypoxia (CH) for 3 weeks can accelerate the development of atherosclerosis in ApoE KO mice." (PMID 37324194, 2023). "A study focusing on atherosclerosis demonstrated that EPA-PL exhibited superior improvement in atherosclerotic lesions induced by a high-fat diet in apoE-/- mice compared to DHA-PL." (PMID 37504940, 2023). "For example, overexpression of human AR (hAR) in the endothelium (and systemically) of an apoE-null mouse accelerates atherosclerosis in a streptozotocin diabetic setting and in an ARI-sensitive manner." (PMID 38132854, 2023). "Further, inhibition of AGEs-RAGE interaction by administration of a recombinant soluble form of RAGE or knockout of RAGE gene has been reported to inhibit the development and progression of atherosclerosis in apolipoprotein-E null (Apoe−/−) mice." (PMID 37047475, 2023). "To that end, we selected ApoE−/− mice that were given a long-term high-fat diet, which is the most commonly used animal model to simulate atherosclerosis." (PMID 38041095, 2023). "To provide an in vivo evidence regarding the role of Morrbid in monocyte–macrophage differentiation, we first applied ApoE knockout mice with atherosclerosis induced by a Western diet for 12 weeks as described in our previous publications." (PMID 37426471, 2023). "Fucoidan has also been found to reduce NPC1L1 expression, inhibit cholesterol uptake in the intestine, and prevent hyperlipidemia-induced atherosclerosis in apoE−/− mice." (PMID 38132943, 2023). "Paradoxically, both genetic deletion and overexpression of eNOS enhanced atherosclerosis in ApoE−/− mice, which was explained by eNOS uncoupling induced by eNOS overexpression." (PMID 37553374, 2023). "In ApoE−/− mice, the IR substrate-2 knockout was protective against atherosclerosis, with mice presenting smaller lesions." (PMID 37849988, 2023). "We used male ApoE−/− mice fed a high-fat diet to establish an animal model of atherosclerosis and then collected blood vessel tissue to extract lipids for mass spectrometry analysis." (PMID 36600244, 2023). "In the experimental atherosclerosis model, we also found reduced levels of miR‐15a‐5p and miR‐199a‐3p in the aorta of ApoE−/− STD or HFD." (PMID 37605307, 2023). "Several experimental studies have focused on investigating the effects of low-dose radiation using mouse models of atherosclerosis, specifically genetically modified ApoE knocked out (KO) mice fed a chow diet." (PMID 37711550, 2023). "We first investigated the effects of chronic shifts of the light-dark cycle on the sizes of atherosclerosis lesions in male and female ApoE−/− mice." (PMID 37064902, 2023). "At 45 weeks, ApoE−/−/IL-4−/− mice had a significant decrease of 58% and 64% of atherosclerosis located in the aortic arch compared to ApoE−/− and ApoE−/−/IL-12−/− mice, respectively." (PMID 37681883, 2023). "Of note though, ApoE is also highly produced and secreted by hepatocytes, and plays crucial roles in regulating peripheral lipid homeostasis and preventing atherosclerosis." (PMID 37580702, 2023).
atherosclerosis (continued). "Adipophilin and PLIN2 have been reported to correlate with atherosclerosis, their expression was compared among the plaques of ApoE−/−, ApoE−/−: Sirt6−/− and ApoE−/−: Sirt6Tg mice." (PMID 37736721, 2023). "In a knockout mouse model of atherosclerosis apolipoprotein-E (ApoE), plasma H2S levels were significantly reduced." (PMID 37046987, 2023). "Using an ApoE−/− atherosclerotic mice model fed a high-fat diet, we investigated the impact and potential mechanism of dandelion polysaccharides on atherosclerosis." (PMID 37836404, 2023). "In conclusion, this study revealed that LCACs aggravated PS‐NP‐induced atherosclerosis by upregulating MARCO in ApoE−/− mice fed with HFD." (PMID 37144527, 2023). "Our previous results suggest that C8:0 can inhibit inflammation and improve atherosclerosis through the TLR4/NF-κBp65 signaling pathway in apoE−/− mice." (PMID 36904298, 2023). "For atherosclerosis plaque imaging, an animal model with plaque along the carotid artery was established with ApoE–/– mice with high fat and cholesterol diet." (PMID 37783733, 2023). "It is thus unsurprising that ApoE knockout mice have often been used in the study of atherosclerosis." (PMID 37762360, 2023). "Atherosclerosis in ApoE(−/−) mice is reduced when ferroptosis is inhibited and iron intake is limited." (PMID 37791060, 2023). "In ApoE−/− mice fed a high-fat diet, naringin significantly alleviated atherosclerosis and reduced the serum and liver cholesterol levels by 24.04 and 28.37%, respectively." (PMID 36823573, 2023). "By RT‐qPCR, we analysed miR‐9‐5p, miR‐15a‐5p, miR‐16‐5p and miR‐199a‐3p levels in aorta from apolipoprotein knockout (ApoE−/−) mice, an experimental model of hyperlipidemia‐induced atherosclerosis, and in human aortic and carotid atherosclerotic samples." (PMID 37605307, 2023). "In a mouse model of atherosclerosis, Cdh11 expression was increased in atherosclerotic plaques of ApoE−/− mice." (PMID 37944753, 2023). "In our previous work, which focused on the modulation of aortic relaxation by perivascular adipose tissue (PVAT), we concluded that the apoE−/− rat serves as a model for early-stage atherosclerosis." (PMID 38079017, 2023). "To verify the role of Morrbid in monocyte–macrophage differentiation in vivo, we first applied ApoE knockout mice with atherosclerosis." (PMID 37426471, 2023). "A recent study has found that CUMS promoted atherosclerosis in ApoE-/- mice, but the mechanism needs to be investigated further." (PMID 37692113, 2023). "CircRNA_ABCA1 expression was increased in aortic vessels of HFD-induced apoE-/- mice and H2O2-induced mouse aortic endothelial cells (MAECs) injury model, suggesting that circRNA_ABCA1 is a potential diagnostic biomarker for atherosclerosis." (PMID 37324939, 2023). "Using apolipoprotein E knockout mice (ApoE-/-) (fed with Western diet) that developed advanced atherosclerosis and using human carotid endarterectomy, we showed that LRG1 accumulated into an atherosclerotic plaque, preferentially in calcified areas." (PMID 38003727, 2023). "Raloxifene, a STAT3 phosphorylation inhibitor, protects against high-fat-induced atherosclerosis in ApoE−/− mice and rabbit." (PMID 36807553, 2023). "Although at very high pharmaceutical doses, β-cyclodextrin treatment reduced plaque size and facilitated atherosclerosis regression through macrophage reprograming in ApoE−/− mice." (PMID 37863894, 2023). "In apolipoprotein E knockout (ApoE−/−) mice fed a high-fat diet, atherosclerosis was induced by partial carotid ligation." (PMID 36750553, 2023).
atherosclerosis (continued). "For example, the sGC stimulator Riocuguat attenuated atherosclerosis in Western diet fed Apolipoprotein E knockout (ApoE-/-) mice." (PMID 37502180, 2023). "Together these data demonstrate that female ApoE−/− mice have increased atherosclerosis when exposed to chronic LD shifts due to increased VLDL/LDL cholesterol, independent of changes in energy balance or feeding-fasting cycles." (PMID 37064902, 2023). "A study investigated the role of IL-1β in the progression of atherosclerosis by engineering double-knockout mice (ApoE-/-/IL-1β-/-)." (PMID 36851139, 2023). "In fact, ApoE-/- mice has been widely used for spontaneous atherosclerosis since ApoE-/- mice accumulate high levels of cholesterol in the blood and thus develop atherosclerosis." (PMID 36852396, 2023). "Media collagen content doubled in the thoracic aortas of ApoE−/− mice, compared to control animals (38.4 ± 7.7% vs. 89.3 ± 3.6%, p < 0.001), showing significant vascular remodeling in atherosclerosis." (PMID 37894941, 2023). "In vivo study demonstrated RAP@T/R NPs significantly blocked the development of atherosclerosis and suppressed the systemic and local inflammation in ApoE−/− mice." (PMID 36683743, 2023). "In this study, atherosclerosis was selectively induced in the LCA via partial ligation of carotid arteries in high‐fat‐diet ApoE−/− mice." (PMID 37476064, 2023). "Activation of renin-angiotensin system (RAAS) also aggravated atherosclerosis in experimental renal failure apoE−/− mice and upregulated IKK phosphorylation in Ang II-stimulated RAW264.7 macrophages." (PMID 36823573, 2023). "The genetically modified apolipoprotein E-knockout (ApoE−/−) mice exhibit poor lipoprotein clearance, being prone to atherosclerosis development." (PMID 37444314, 2023). "Other studies have shown that in mice with apolipoprotein E deficiency, FABP-4 gene deficiency protects these mice from atherosclerosis; therefore, FABP-4 inhibition effectively treats atherosclerosis in a mouse model." (PMID 38024104, 2023). "Even a transient increase in SAA mediated by adenoviral vector gene delivery results in significantly increased atherosclerosis in apoE−/− mice." (PMID 37004910, 2023). "In summary, we demonstrated that atorvastatin prevents development of hepatic steatosis, inflammation and fibrosis in APOE*3-Leiden mice, a model that develops atherosclerosis and NASH upon WTD-feeding." (PMID 37175538, 2023). "In our research, tight junction proteins were found signally downregulated in aged ApoE-/- mice, consistent with the declined level of ZO-1 in the model of atherosclerosis (ApoE-/- mice) reported by Yan." (PMID 38048213, 2023). "Th17/Treg function is imbalanced during high-fat diet-induced atherosclerosis in age and apolipoprotein E (ApoE)-/- mice, and Porphyromonas gingivalis oral infection further exacerbated Th17/Treg imbalance and atherosclerosis plaque deterioration." (PMID 36911741, 2023). "In conclusion, we found that ANGPTL8 knockout significantly inhibited the progression of AAA and atherosclerosis in ApoE−/− mice." (PMID 37294581, 2023). "Intermittent hypoxia and hypercapnia accelerated the development of atherosclerosis in ApoE-/- mice." (PMID 37324194, 2023). "It has also been shown that infusion of purified spleen Tregs reduced atherosclerosis and induced a more stable plaque phenotype in ApoE-/- mice." (PMID 36761778, 2023).
atherosclerosis (continued). "Desulfovibrio desulfuricans aggravates atherosclerosis by increasing intestinal permeability and circulatory lipopolysaccharide in a mouse model of atherosclerosis (ApoE−/− mice)." (PMID 37627522, 2023). "A mouse model of disturbed blood flow‐induced atherosclerosis was established by the partial ligation of the left carotid artery (LCA) in an ApoE KO mice that were fed a high‐fat diet." (PMID 37476064, 2023). "The same technology was used to generate apoE −/− rats which develop extended atherosclerosis with the administration of a Paigen diet for 64 weeks." (PMID 39802625, 2023). "In advanced human atherosclerotic lesions and ApoE knock-out mice lesions, genomic hypomethylation occurs with atherosclerosis." (PMID 38031118, 2023). "HIVposEVs, but not HIV PLdepEVs or HIVnegEVs (EVs from HIVneg individuals), increased atherosclerosis in apoE−/− mice, which was accompanied by elevated senescence and impaired functionality of arterial cells and lin− BMCs." (PMID 37108729, 2023). "Oral administration of geniposide, a monoterpenoid isolated from the traditional Chinese herb Gardenia jasminoides, was shown to ameliorate the development of atherosclerosis in HFD-fed ApoE−/− mice." (PMID 36768748, 2023). "In this study, we aim to further characterize the apoE−/− rat model and investigate its feasibility as an in vivo model for atherosclerosis (PET/CT) imaging." (PMID 38079017, 2023). "In the atherosclerosis-prone ApoE−/− mice, GSDME protein and mRNA levels were significantly increased after feeding high-fat diet for 12 wk." (PMID 36807553, 2023). "We evaluated the effect of PS‐NPs on atherosclerosis with an in vivo model, which was achieved by daily gavage of PS‐NPs on ApoE−/− mice fed with HFD." (PMID 37144527, 2023). "Among the isoforms of apolipoprotein E (APOE), APOE4 has been recognized as a risk factor for the cardiovascular system, which increases the risk of atherosclerosis by increasing LDL levels." (PMID 37350790, 2023). "ApoE−/−/Cdh11−/− double knockout mice had altered immune cell populations and increased atherosclerosis." (PMID 37944753, 2023). "Overexpression of GPX4 significantly reduces lipoperoxide and atherosclerosis progression in ApoE(−/−) mice." (PMID 37791060, 2023). "Both heme-oxygenase 1 and ferritin were also expressed in erythrocyte-rich regions of carotid plaques from ApoE−/−Fbn1C1039G+/− mice, a model of advanced atherosclerosis with IP angiogenesis." (PMID 37120604, 2023). "The animal experiment results suggested that CKN can effectively prevent the development of atherosclerosis in ApoE−/− mice by upregulating ABCA1 expression in macrophages." (PMID 37322486, 2023). "S-aspirin (ACS14), a H2S-releasing form of aspirin, also protects ApoE−/− mice against atherosclerosis." (PMID 37373103, 2023). "Overexpression of SAA using a murine lentivirus accelerates the progression of atherosclerosis in apoE−/− mice." (PMID 37004910, 2023). "Apolipoprotein E-deficient mice null for FABP4 shows reduced atherosclerotic lesions and improved atherosclerosis and survival." (PMID 36769659, 2023). "By analyzing total lipid extracts of plasma and LDL, we aimed to detect molecular fingerprints of apoE−/− and HFD-fed apoE−/− mice for atherosclerosis and CVD." (PMID 37108120, 2023). "In high-fat diet-induced ApoE−/− mice, ferrostatin-1 (Fer-1) mitigated atherosclerosis by preventing ferroptosis and reducing iron accumulation and lipid peroxidation, suggesting the role of ferroptosis in atherosclerosis." (PMID 36771298, 2023). "Grapes and pomegranates have been studied for their potential beneficial effects in ApoE-/- mouse models of atherosclerosis and CVD." (PMID 37108307, 2023). "Our findings are consistent with prior studies that inverting the LD cycle increased atherosclerosis in female APOE*3-Leiden.CETP and low-density lipoprotein receptor knockout mice." (PMID 37064902, 2023).
atherosclerosis (continued). "Endogenous OPG protected ApoE−/− mice from atherosclerosis and VC, and the transgenic expression of RANKL in VSMCs promoted VC in mice." (PMID 37091976, 2023). "Our study clearly shows a role of Hh signaling inhibition in anti-atherosclerosis with reduction of plaque area and lipid content in vismodegib treatment apoE-/- mice." (PMID 37963874, 2023). "In macrophages, H2S-mediated peroxisome proliferator activated receptor gamma (PPARγ) inhibition also inhibits C-X3-C chemokine fractalkine (CX3CL1) signaling in the context of atherosclerosis in ApoE−/− mice." (PMID 37373103, 2023). "One study showed that light-induced circadian disruption also increased atherosclerosis in male ApoE-/ mice." (PMID 37064902, 2023). "In contrast, KCNQ1OT1 silencing protected against atherosclerosis in apoE-/-mice and inhibited the lipid accumulation in THP-1 macrophages." (PMID 38057885, 2023). "Upregulated PSRC1 contributed to reduce the atherosclerosis by regulating the cholesterol transportation in apoE-/- mice." (PMID 35685372, 2022). "The results thus far show the A2Kb-Tg ApoE–/– mouse is a valid humanized atherosclerosis model to investigate translational use of P210-PAM as an antigen-specific immune-modulating therapy." (PMID 35536648, 2022). "Dimethyl fumarate, an example of this category, led to reduction in myocardial infarct size in animal models of myocardial ischemia/reperfusion injury and to prevention of atherosclerosis in apoE−/− mice." (PMID 36295098, 2022). "In susceptible models, this leads to modest hypertension, cardiac hypertrophy, accelerated aortic aneurysms, and augmented atherosclerosis in ApoE KO mice." (PMID 35624851, 2022). "We previously demonstrated that activation of PXR by other ligands including BPA and PCN increased CD36 expression and lipid accumulation in macrophages of ApoE−/− mice in vivo, likely contributing to the increased atherosclerosis in those mice." (PMID 35406689, 2022). "Ginkgolide B (30 mg/kg−1/d−1) administered by gavage can reduce atherosclerosis in apolipoprotein E null (ApoE−/-) mice and inhibit platelet release by blocking the thrombin and collagen activation of the platelet PI3K/Akt pathway." (PMID 35721128, 2022). "Together, therapeutic sclerostin antibody elevated serum levels of inflammatory cytokines and chemokines, aggravated AA and atherosclerosis in Col1a2+/G610C.ApoE-/- mice with AngII infusion." (PMID 35966595, 2022). "Other studies have shown that the involvement of MMPs in atherosclerosis leads to a reduction in atherosclerotic lesions when using double knockout animals for ApoE-⁄- and MMP-2-⁄-, MMP-8-⁄-, and MMP-9-⁄- and MMP-12-⁄-." (PMID 35269673, 2022). "To carry out this objective, we have used a classic experimental model of atherosclerosis, ApoE−/− mice under a standard diet (STD) or a high-fat diet (HFD) for 8 and 18 weeks." (PMID 36142173, 2022). "To address this issue, we employed (i) human non-atherosclerotic and atherosclerotic tissue specimens, (ii) in vivo experimental model of atherosclerosis, namely ApoE-/- mice, and (iii) in vitro polarized M1/M2-Mac derived from primary cultures of mouse Mon." (PMID 36552592, 2022). "Genetic overexpression of SIRT6 in VSMCs delayed senescence and inhibited atherosclerosis in HFD-fed ApoE-/- mice." (PMID 35855341, 2022). "A marked increase in atherosclerotic lesion area was demonstrated in the aortas of Stamp2-/-ApoE-/- mice, a model system to study atherosclerosis." (PMID 36140186, 2022).